NAPSB (napsin B aspartic peptidase (pseudogene))
Synonyms: NAP1L; NAP2; NAPB; NAPSBP
Gene: Transcribed unprocessed pseudogene on chromosome 19 (50,333,877 to 50,344,761, reverse strand). Ensembl gene ENSG00000131401.
Diseases named in the same sentence as NAPSB in open-access papers:
NAPSB is named in the same sentence as 12 diseases in open-access papers, as found by Europe PMC text mining. Sharing a sentence is not in itself a finding about the gene and the disease. The quoted sentences say what the papers report.
sarcoma (2 papers, 2021 to 2022). A usually aggressive malignant neoplasm of the soft tissue or bone. "One bioinformatic analysis reported that the overexpression of the lncRNAs ADAM6, C5orf58, CXCR2P1, FCGR2C, HCP5, HLA-H, NAPSB, NCF1B, and NCF1C reduced the sensitivity of sarcoma to ICIs." (PMID 36326232, 2022). "The expression of nine ICLs, ADAM6, C5orf58, CXCR2P1, FCGR2C, HCP5, HLA-H, NAPSB, NCF1B and NCF1C, was further investigated in different cancer types, including sarcoma." (PMID 34178688, 2021).
glioma (1 paper, 2022). A benign or malignant brain and spinal cord tumor that arises from glial cells (astrocytes, oligodendrocytes, ependymal cells). "Few articles study the relationship between glioma prognosis and SVOP or NAPSB, which need to be further studied." (PMID 36091778, 2022).
hepatocellular carcinoma (1 paper, 2022). A malignant tumor that arises from hepatocytes. "However, the biological role of NAPSB in hepatocellular carcinoma (HCC) remains to be determined." (PMID 35987606, 2022).
pancreatic ductal adenocarcinoma (1 paper, 2022). An infiltrating adenocarcinoma that arises from the epithelial cells of the pancreas. "Napsin B Aspartic Peptidase, Pseudogene (NAPSB) is a pseudogene that has been identified to be associated with the infiltration of CD4 + T immune cells in pancreatic ductal adenocarcinoma (PDAC)." (PMID 35987606, 2022). "Napsin B Aspartic Peptidase, Pseudogene (NAPSB) was associated with CD4 + T cell infiltration in pancreatic ductal adenocarcinoma." (PMID 35987606, 2022).
cancer (3 papers, 2021 to 2022). A tumor composed of atypical neoplastic, often pleomorphic cells that invade other tissues. "NAPSB was positively correlated with immunomodulators, tumor-infiltrating immune cells, T cell inflamed score and cancer-immunity cycle, and highly expressed in immuno-hot tumors." (PMID 35987606, 2022). "Since both TIS and cancer-immunity cycle reflect the T cell infiltration and anti-cancer immune response of human body, these results reaffirmed and extended the close relationship between NAPSB and an immune-hot and inflamed TME." (PMID 35987606, 2022). "These evidences reconfirmed that NAPSB may be a valuable predictor of immunotherapy response across cancers." (PMID 35987606, 2022). "Finally, we evaluated the correlation between NAPSB and seven steps of cancer-immunity cycle, which conceptualized the anti-cancer immune response." (PMID 35987606, 2022). "Additionally, we observed NAPSB was positively related to the TIS, as well as several critical steps of the cancer-immunity cycle." (PMID 35987606, 2022). "NAPSB was found to upregulate the expression of critical immunomodulators (including MHC, immunostimulators, chemokines and receptors), which may upregulate the activities of the cancer-immunity cycle subsequently." (PMID 35987606, 2022). "In summary, these data consistently indicated that high expression of NAPSB was to transform a non-inflamed TME into an immuno-hot and inflamed TME, consequently triggering anti-cancer immune response." (PMID 35987606, 2022).
tumor (2 papers, 2021 to 2022). "Given that cell death had been reported in recent years to play a significant role in tumor therapy, we investigated the association between NAPSB and various forms of cell death, including pyroptosis, necroptosis, apoptosis, autophagy and ferroptosis." (PMID 35987606, 2022). "The expression of NAPSB was compared between hot and cold tumors, and we found that it was overexpressed in hot tumors, suggesting that NAPSB could play a role in distinct hot/cold tumor states and be associated with therapeutic response to immunotherapy." (PMID 35987606, 2022). "We found these scores were significantly increased in the NAPSB-high group, while tumor purity was negatively correlated with the expression of NAPSB." (PMID 35987606, 2022). "Here, NAPSB was highly expressed in hot tumor samples consistently." (PMID 35987606, 2022). "The results showed that NAPSB and CXCL9 were upregulated in PDAC tumor tissues with statistical significance." (PMID 34367961, 2021). "NAPSB was correlated with an immuno-hot and inflamed TME, and tumor cell death." (PMID 35987606, 2022).
neurogenetic diseases (1 paper, 2024). "Regarding cDC1s, the genes associated with MHC II antigen presentation (HLA-DRB5, IFI30), immune activation (NAPSB), and developmental and neurogenetic diseases (NBPF14) were highly expressed in active TAO compared to NCs." (PMID 38728262, 2024).
NAPSB also shares sentences with these, for which no sentence is quoted: bladder urothelial carcinoma (1 paper); colon adenocarcinoma (1); lung adenocarcinoma (1); lung squamous cell carcinoma (1); rectal adenocarcinoma (1).